MET (MET proto-oncogene, receptor tyrosine kinase)
Diseases named in the same sentence as MET in open-access papers (continued):
Sharing a sentence is not in itself a finding about the gene and the disease.
cancer (continued). "In this study we have identified THEMIS2 as a novel modulator of cancer stemness and chemoresistance, revealed its regulatory mechanism in MET activation, and suggested a relevant clinical application using CPT or Capmatinib to target THEMIS2/MET axis." (PMID 34974522, 2022). "The studies indicated that targeting MET, AXL, and VEGFR2 may enhance the efficacy of immune checkpoint inhibitor for cancer patients, which can be explored in further study." (PMID 36341335, 2022). "In addition, NF-κB downstream effectors, such as CCND1, CCNE2, MET, VEGFA, CD44 and CD133, contribute to cancer proliferation, metastasis and stemness, and their expression is regulated by PCDH1." (PMID 35864095, 2022). "As CCL2/CCR2 activated SRC and SRC interacts with MET to regulate receptor activation in carcinoma cells, we asked whether CCL2-mediated SRC activation was important for MET phosphorylation." (PMID 35405500, 2022). "What is more, overexpression of miR-34 could reduce the expression levels of MET and CDK6 which have interaction with PI3K/AKT signaling in cancer cells." (PMID 33796457, 2021). "Similar to MET amplification, RET kinase domain activation leads to the oncogenic signaling of BRAF-MEK-ERK, PI3K-AKT-mTOR and JNKs pathways, favoring cell survival and cancer development." (PMID 35004309, 2021). "The gene for ILEI, FAM3C, is located close to MET on chromosome 7q31 in an amplification “hotspot”, but it is unclear whether FAMC3 amplification contributes to elevated ILEI expression in cancer." (PMID 33596971, 2021). "ILEI KD did not influence the proliferation of the cell lines suggesting that ILEI is not involved in proliferation of cancer cells or c-MET-regulated proliferation." (PMID 33596971, 2021). "Once we had established that MET and FAM3C were often co-amplified and this led to combined overexpression of c-MET and ILEI, it was important to investigate whether they interact during cancer progression." (PMID 33596971, 2021). "Kinase inhibitors have shown great potential as a TNBC regimen due to their activity as antitumor and antiangiogenic therapies by targeting genes and pathways that play a role in cancer development and proliferation, like targeting EGFR, RON, MET, mTOR, BRAF, MEK, Src, and Bcr/Abl." (PMID 34944904, 2021). "In addition, overexpression of DRs such as PlexinD1, NOTCH3, c‐KIT, c‐MET, PTCH‐1, or TrkC has been reported in several cancer types, in contexts where their ligands are also expressed." (PMID 34542930, 2021). "Therefore, the clinical relevance of this frequent cancer amplification hotspot, so far dedicated purely to c-MET function, should be re-evaluated to include ILEI as a target in the therapy of c-MET-amplified human carcinomas." (PMID 33596971, 2021). "This study describes an approach to distinguish focal and non-focal MET amplification using unfiltered data from comprehensive genomic profiling of cfDNA in advanced cancer patients." (PMID 34677235, 2021). "Generally, MET is thought to play a central role in signaling pathways to control cell proliferation, survival, and migration, in response to binding by its ligand HGF during developmental morphogenesis and in multiple cancer types." (PMID 34202288, 2021). "Moreover, the alteration in expression levels of other molecules such, c-MET, RAS/BRAF, EGFR/ERBB2 which are involved downstream, affect cancer cell proliferation and development." (PMID 33777535, 2021). "LMS1 was further characterized by several oncogenic signatures in the MAPK and MET signaling pathways (including KRAS and BRAF signatures), as well as cancer aggressiveness (cell migration, hypoxia) and a signature of resistance to the standard chemotherapeutic agent 5-fluorouracil." (PMID 34470666, 2021). "This study describes an approach to distinguish focal and non-focal MET amplification using comprehensive genomic profiling of cfDNA in advanced cancer patients." (PMID 34677235, 2021).
cancer (continued). "In addition, today novel drugs targeting c-MET or HGF are being developed and tested in ongoing or completed clinical trials in other cancer-cell types." (PMID 35582373, 2021). "MET is a single transmembrane receptor PTK with important roles in promoting cell growth and differentiation during embryonic development, organogenesis, and cancer progression." (PMID 34590584, 2021). "We next used the KTC1 and PDX.008.CL cell lines, as well as the metastatic patient sample to quantify copy number and expression of several cancer-related genes located on chromosome 7p and 7q, including RAC1 (7p22.1) TWIST1 (7p21.1), EGFR1 (7p11.2), MET (7q31.2) and BRAF (7q.34)." (PMID 34638434, 2021). "Thus, several MET-targeting agents, including HGF and MET antibodies, as well as small molecule kinase inhibitors, are currently envisaged as anti-cancer therapeutics." (PMID 34925346, 2021). "MET is involved in the activation of multiple signal transduction pathways, including RAS, PI3K and -catenin pathways, which play an important role in the occurrence and development of cancer." (PMID 34123778, 2021). "As initial assessment of MET gene expression in human MM, we looked at the expression of the MET mRNA in the public GEPIA database for gene expression profiling analysis in the different cancer types sampled for “The Cancer Genome Atlas” (TCGA) project." (PMID 34884673, 2021). "It was reported that diffuse or mixed-type cancers were mostly c-MET-negative, and the score of IHC2+ was correlated with intestinal-type GC and less advanced TNM stages than those with IHC-negative." (PMID 35076580, 2021). "MET is a receptor tyrosine kinase (RTK) that, when bound by its ligand hepatocyte growth factor (HGF), coordinates a programme of invasive growth that broadly overlaps with the process of EMT, both in cancer and during the physiological process in development." (PMID 33772015, 2021). "HGF, which is well known for its correlation to cancer aggressiveness and poor prognosis, is commonly overexpressed in solid tumors and acts as a single ligand for the MET proto-oncogene, receptor tyrosine kinase (c-Met) surface receptor." (PMID 34514097, 2021). "The co-occurrence of MET and KRAS or MET and PIK3CA might increase the aggressiveness of cancer cells, including cell proliferation, survival, invasion, or metastasis." (PMID 34439385, 2021). "GSEA indicated that multiple cancer signaling pathways (mTOR pathway, GSK3 pathway, EIF4 pathway, CHREBP2 pathway, MET pathway, NFAT pathway, FAS pathway, EDG1 pathway, AKT pathway, and CTCF pathway) were differentially enriched in YTHDF2 increased expression phenotype." (PMID 33102202, 2020). "Nowadays, cancer patients are routinely treated with therapeutic agents such as erlotinib and gefitinib to suppress EGFR signaling or crizotinib and cabozantinib targeting MET." (PMID 32316583, 2020). "HiP-8 could selectively detect active HGF in cancer tissues, and active HGF probed by HiP-8 showed co-localization with activated MET." (PMID 33121208, 2020). "Responses to either ICG-001 or DAPT did not correlate with the pathological stage or grade of the cancer or percentage of CXCR4+MET+CD44+ cells indicating that specific mechanisms of response exist." (PMID 32066735, 2020). "Some oncogenes such as MET and CTNNB1 showed slight overall negative enrichment, but their nonsynonymous mutations, especially in specific cancers, showed enrichment during periods of positive growth." (PMID 32024824, 2020). "In addition to enumerating CTCs, we investigated potent cancer biomarkers such as PDL1 and MET in the isolated CTCs." (PMID 32486306, 2020). "The signaling pathways we identified in ND MSCs were replaced by MET, WNT, and FGFR2 signal transduction, which may play a role in promoting inflammation, cancer, and aging." (PMID 33361524, 2020). "MET, EGFR and STAT3 function as oncogenes in many types of malignant tumors including NSCLC." (PMID 33318313, 2020).
cancer (continued). "The selective inhibition of MET activation has been anticipated to become a molecular-targeted therapy of cancer, although no selective inhibitors of HGF-MET have been approved as drugs for cancer." (PMID 33121208, 2020). "HER2 is rarely amplified or mutated in HNSCC/LUSC31, but this activation through polymorphic MET may lead to constitutive HER2 signaling and drive these cancers." (PMID 32214092, 2020). "MET is a receptor for hepatocyte growth factor (HGF), and its overexpression is related to the process of metastatic dissemination and drug resistance in several cancers, resulting in poor prognosis." (PMID 32486306, 2020). "Studies with our 3D organotypic cultures (involving the seeding of cancer cells on top of PSC-containing collagen matrices) showed that inhibition of HGF and c-MET (either alone or in combination) did not alter cancer cell proliferation." (PMID 32203220, 2020). "Since MACC1 is a positive regulator of c-MET, a receptor for hepatocyte growth factor, circ-PDE8A activates downstream signaling factors, such as Akt and ERK1/2, thereby promoting invasive growth and metastasis of cancer cells." (PMID 32756339, 2020). "Among these genes, elevated expression in cancer tissues was observed for MET and ERBB2, but neither of them predicted patient survival." (PMID 32807134, 2020). "Also, cabozantinib was found to inhibit SOX2, c-MET, and CD133 expression and the self-renewal potential of cancer cells." (PMID 33271944, 2020). "Most of the mutations of MET, TSC2, and RB1 that were detected in cohort 1 of this study were private and would therefore not qualify for a broadly applicable “off-the-shelf” cancer vaccine or ACT approach." (PMID 32228647, 2020). "Novel cMet‐targeting therapies, such as ADCs, are in development, which are independent of MET amplification status and target any cMet‐overexpressing cancer." (PMID 31736230, 2020). "KRAS activation is an important mechanism of innate and acquired drug resistance, but resistance may also be mediated through other signaling networks such as MET, HER2/3, BRAF, and PIK3CA, which share the same mechanisms in other cancers." (PMID 30700700, 2019). "HGF acts mainly as a paracrine factor rather than as an autocrine activator of MET in HNC, and because it is secreted by cancer-associated fibroblasts, it is abundant in the tumor microenvironment." (PMID 30700700, 2019). "Inhibition of c-MET signaling may impair cancer cell growth and at the same time stimulate immune responses via relieving HGF/c-MET induced immunosuppressive effects on mono-macrophages and on T cells." (PMID 30642077, 2019). "Importantly, MET and CDK4/6 inhibition synergistically reduced Ki-67 expression across a set of cancer cell lines, with diverse tissues-of-origin and genetic driver profiles." (PMID 31296956, 2019). "c-MET, a high-affinity receptor for hepatocyte growth factor (HGF), is deregulated in many cancers." (PMID 30850583, 2019). "A recent clinical trial (ClinicalTrials.gov Identifier: NCT02034981) has been initiated to assess the efficacy of crizotinib in cancer patients identified with amplication of crizotinib target genes—anaplastic lymphoma kinase (ALK), MET or ROS proto-oncogene 1 (ROS1) positive." (PMID 31766284, 2019). "The previously published data also indicated that there was no obvious MET activation/phosphorylation in cancer cell lines A549, MDA-MB-231 and DLD1, which shares the same genetic origin with HCT-15." (PMID 31137515, 2019). "The compound 12c caused low micromolar concentration inhibition of the cell viability of all cancer cells and exhibited the best antineoplastic activity at 25 μM no matter MET is activated or not." (PMID 31137515, 2019). "Furthermore, H19 regulated many other cancer-related genes in this network, such as AKT3, CSF1, MET, COL1A1, COL5A1, WWTR1, EPHB4, and TMPRSS3." (PMID 31164794, 2019).
cancer (continued). "The carcinoma with plasmacytoid morphology of the stomach presented, in our material, several negative prognostic factors: age over 50, advanced stage (both pTNM and Dukes-MAC like), angiolymphatic invasion, EMT phenotype, and positivity for c-MET and CD44." (PMID 31205468, 2019). "Our case series showed that, in gastrointestinal tract, carcinoma with plasmacytoid morphology is an aggressive “mesenchymal-type poorly cohesive carcinoma” that expresses c-MET but not HER-2." (PMID 31205468, 2019). "Finally, as the HD753 sample harbors two previously characterized amplifications in the MET and MYC cancer drivers, both of which are present in the 130-gene assay, we assessed the performance of the 130-gene panel in identifying CNAs." (PMID 29354287, 2018). "In conclusion, our findings could suggest that LAMB3 contributes to cancer cell migration and invasion in PTC via c-MET/Akt signaling." (PMID 29426928, 2018). "Amplification of many RTKs occurs in a variety of human cancers, such as EGFR, ERBB2 and MET." (PMID 29455648, 2018). "The generation of a MET/HGF autocrine loop by anomalous co-expression of ligand and receptor in the same cell is another way by which cancer cells may achieve continuous MET activation." (PMID 30544501, 2018). "HGF reactivates MET, EGFR and RON phosphorylation and restores AKT, ERK and WNK1 signaling upon MET inhibition, promoting the survival of MET-inhibited cancer cells." (PMID 28968967, 2017). "These TCGA data analyses may support the hypothesis that the co-amplified genes identified as potential CPGs for GC in this study play pro-oncogenic roles in other cancers as well, similar to ERBB2 and MET." (PMID 29190909, 2017). "Cancer cell invasion was abrogated when treating the cells with the low molecular weight inhibitor crizotinib (Xalkori®, Pfizer), that targets the RTKs ALK, MET and ROS." (PMID 29296175, 2017). "Since our results showed a dual inhibitory role of miR-206 in c-MET and EGFR expression in NRF2-silenced SKOV3 and A498 cells, we asked whether this was a common biological link in other types of cancer cells." (PMID 29291022, 2017). "In a significant number of human cancers, HGF/SF and MET are overexpressed." (PMID 28061464, 2017). "The implications of synchronous presence of aberrantly active MET and PIK3CA mutations in cancer has not been previously explored." (PMID 28532501, 2017). "As a first step in defining the determinants of MET dependence, we correlated the IC50 values for the MET inhibitor crizotinib with MET gene expression and amplification using publicly available data from the Cancer Cell Line Encyclopedia (CCLE) project." (PMID 28881678, 2017). "While MET-amplified cancer cells do not respond to EGFR-targeting drugs, they are uniquely sensitive to anti-MET therapy." (PMID 28420162, 2017). "Moreover, we and others have demonstrated that inhibition of both MET and HGF is required to overcome therapeutic resistance in MET-amplified cancer cells." (PMID 28420162, 2017). "Several c-MET inhibitors are being evaluated in clinical trials for various cancer types including PDAC, with promising results still lacking, presumably due to poor patient selection and de novo resistance." (PMID 28445954, 2017). "The MET and EGFR tyrosine kinases are actionable therapeutic targets due to their high expression in TNBC and availability of several selective kinase inhibitors that are either FDA approved for other cancers or are in clinical trials." (PMID 27655711, 2016). "In this study, we show that ddPCR is a quantitative method that can absolutely quantify the MET copy number in cancer samples either in vitro or in vivo, without the need for standard curves or endogenous control." (PMID 26765781, 2016). "However, EGFR can also bind with MET and PDGFR, thereby constituting a diversified signal transduction network in cancer cells." (PMID 27013592, 2016).
cancer (continued). "The binding of MET with its ligand (hepatocyte growth factor) activates downstream signaling pathways, including phosphoinositide 3-kinase (PI3K)/Akt, Ras-Rac/Rho, MAPK, and phospholipase C-γ, frequently activated in human cancers." (PMID 26918450, 2016). "In addition to VEGFRs/MET signaling, FMS signaling is reported to have pivotal roles not only in bone metabolism but also in cancer bone metastasis." (PMID 27736957, 2016). "Cancer cells with amplified MET, which normally display HGF-independent MET activation, become dependent on HGF when MET kinase activity is inhibited, suggesting that HGF may also be associated with resistance to drugs that target MET." (PMID 27121052, 2016). "The Hepatocyte Growth Factor Receptor (MET) is a tyrosine kinase that is known to participate in inflammatory responses and is critical for the self-renewing capability of stem cells in several cancers." (PMID 27798657, 2016). "To investigate cell proliferation effects of c-MET inhibition by INC280, we tested the proliferation rates of untreated OVCAR3, SKOV3 and CaOV3 cancer cells, as well as the normal ovarian surface epithelium HOSE 6.3 cells, with HGF, HGF + INC280, and INC280 treatments." (PMID 26138303, 2015). "In order to define the molecular mechanism involved in contact-dependent fibroblast-induced cancer cell elongation, migration and invasion, we applied pharmacological inhibitors of several known invasion-promoting kinases (i.e. PI3K/AKT, c-MET, MAPK/ERK, EGFR or FGFR) to co-cultures." (PMID 25973543, 2015). "Since tumorigenesis may involve the dysregulation of the MET signaling pathway, changes in HGF or MET signaling are expected to be potential biomarkers for understanding cancer development and the effect of drugs." (PMID 28536405, 2015). "The involvement of MET and VEGFR signalling in bone remodelling and metastasis offers the opportunity for therapeutic targeting of the bone microenvironment in addition to the cancer itself." (PMID 26279137, 2015). "Should HGF- or MET-directed therapy prove to be an effective treatment option for patients with GEC, experience with other RTK inhibitors suggests that resistance will invariably develop even in the subset of cancers that initially derive clinical benefit." (PMID 24930887, 2014). "HGF-induced MET activation as a mechanism of attenuated sensitivity to cetuximab in CRC has been reported by preclinical studies using either CRC cell lines or, more recently, CRC spheroids enriched in cancer stem cells." (PMID 24811491, 2014). "According to the result, Crizotinib inhibited the phosphorylation of c-MET only in c-MET amplification cancer cells, and not in other types of c-MET alternated cancer cells." (PMID 25193856, 2014). "In cancer cells with high MET activity, inhibition of EGFR activity alone likely is not sufficient to abrogate STAT3 activity." (PMID 24662938, 2014). "The negative effect of higher MET gene copy number on the overall survival of patients with NSCLC can be explained by the role of MET in cancer biology." (PMID 25232729, 2014). "Because of the widespread expression of MET and HGF in cancer, their expression has been analyzed for cancer severity, and the degrees of expression of MET and HGF are believed to indicate the progression of disease as well as serve as prognostic markers for some forms of cancer." (PMID 28548073, 2014). "Interestingly, the ether bridge of DDR1-IN-1 is also found in the MET (hepatocyte growth factor receptor) inhibitor LY2801653, which has entered clinical trials for advanced cancer and inhibits DDR1 with IC50 and EC50 values of less than 1 nM." (PMID 24768818, 2014). "Consistent with expectations, canonical luminal genes such as ESR1, GATA3, FOXA1, TFF1 and IGF1R were higher in ER+ samples compared to triple negative samples, while proliferation and mesenchymal genes such as SPRY2, SNAI2, FOSL1, MET and BUB1 were higher in triple negative cancers." (PMID 24520381, 2014).